INS (insulin)
Diseases named in the same sentence as INS in open-access papers (continued):
Sharing a sentence is not in itself a finding about the gene and the disease.
Hyperinsulinemia (continued). "Evidence suggests that there is a good consistency between the increase in islet DNA content and serum insulin levels indicating that islet hyperplasia plays a role in the development of hyperinsulinemia in Zucker Diabetic Fatty (ZDF) rats." (PMID 27595114, 2016). "In the case of prediabetes, increases of blood glucose stimulate the secretion of insulin and subsequently induce hyperinsulinemia to a normal blood glucose range." (PMID 27200103, 2016). "While the glucose tolerance in GTT performed at 6 weeks was almost equivalent between the two mice models, hyperinsulinemia in GTT or insulin resistance in ITT of GH3-FTY mice tended to be stronger than those of GH3." (PMID 27706259, 2016). "Patients with impaired glucose tolerance presented hyperinsulinemia and delayed peak insulin during OGTT." (PMID 27872738, 2016). "We infer from these results that a reduced clearance of insulin is a factor that contributes to the pathogenesis of the hyperinsulinemia after an oral glucose challenge in obese subjects, thereby confirming previous reports." (PMID 26942445, 2016). "Secondly, excess iron deposition culminates in hyperinsulinemia due to obstruction in the insulin withdrawing ability of the liver." (PMID 29083385, 2016). "Just IR would induce compensatory hyperinsulinemia, and excess insulin would increase insulin growth factor-1 (IGF-1)." (PMID 26770659, 2016). "As a compensatory mechanism, beta cell hyperplasia and/or hypertrophy takes place to increase the insulin secretion that leads to hyperinsulinemia." (PMID 27562101, 2016). "Insulin potentiates steroidogenic response to gonadotrophins both in vivo and in vitro; hence, during hyperinsulinemia there will be elevated androgen levels." (PMID 27672393, 2016). "Salivary insulin predicting hyperinsulinemia occurred in 4.3% of normal-weight adolescents, 8.3% of overweight adolescents, and 25.7% of obese adolescents (p < 0.0001)." (PMID 27069678, 2016). "The ratios of dT under hyperinsulinemia (insulin level = 1) compared to the 0.5 or 0 insulin levels are 1.56 and 2.39, respectively (dTinsulin_1/dTinsulin_0.5 = 67.6/43.3 = 1.56; and dTinsulin_1/dTinsulin_0 = 67.6/28.2 = 2.39)." (PMID 27613445, 2016). "Defects limited to this glucose-lowering action thus produce compensatory hyperinsulinemia, exposing any less-resistant insulin-responsive pathways or tissues to high levels of insulin action." (PMID 27766312, 2016). "On the one hand, it led to the abnormal transport through the blood–brain barrier of leptin and insulin, leading to decreased levels of insulin and leptin in the CNS despite of the existence of hyperinsulinemia and hyperleptinemia." (PMID 27867820, 2016). "Hyperinsulinemia increases growth factor signaling even if the metabolic function of insulin is disturbed." (PMID 27409167, 2016). "In fact, rapamycin increased insulin sensitivity and reduced weight gain in 3 models, and decreased hyperinsulinemia in 2 models." (PMID 27922820, 2016). "Western blot of key insulin signaling intermediates in muscle were examined at baseline and during clamp hyperinsulinemia." (PMID 26916476, 2016). "In vivo, beta cells in the pancreas subsequently increase their production of insulin, further contributing to hyperinsulinemia." (PMID 27101796, 2016). "In contrast, in the PV zone, where Irs1 is abundantly expressed, insulin signalling is rather enhanced in the presence of hyperinsulinemia despite the downregulation of Irs2, resulting in the increased lipogenesis and development of steatosis." (PMID 27708333, 2016). "On the other hand, iron interferes with insulin inhibition of glucose production by the liver and decreases the hepatic extraction and metabolism of insulin, leading to peripheral hyperinsulinemia." (PMID 27077854, 2016). "Compensatory hyperinsulinemia can develop in horses with IR by two mechanisms: increased insulin secretion from the ß-cells in the pancreas and reduced insulin clearance by the liver." (PMID 27766982, 2016).
Hyperinsulinemia (continued). "In accordance with the hyperinsulinemia, insulin staining revealed a significant increase in beta cell mass of ∼twofold in iLIRKO versus control mice at 9 months of age." (PMID 27562101, 2016). "Compensatory hyperinsulinemia is not only related to increased insulin secretion by pancreatic β-cells but also to reduction in insulin clearance." (PMID 27846285, 2016). "These events lead to impaired hepatic insulin clearance and the development of systemic hyperinsulinemia." (PMID 26989445, 2016). "This in vitro study provided a viewpoint of 2DG as a potential therapeutic agent against colorectal cancer, especially for patients with concomitant hyperinsulinemia or treated with exogenous insulin." (PMID 26939025, 2016). "Another potential consequence of prolonged hyperinsulinemia is the exacerbation of inflammation since it has been demonstrated that in vitro, insulin exerts long-term proinflammatory action, by amplifying effects of the cytokine-NFkB axis." (PMID 27437032, 2016). "Fasting insulin levels were also increased by high fat diet, with pronounced hyperinsulinemia in MA mice." (PMID 27694529, 2016). "This correlated with an improvement of impaired insulin sensitivity, which was evident in the HF mice by hyperinsulinemia and impaired glucose tolerance." (PMID 27676071, 2016). "Subtle metabolic derangements were observed in both subgroups, including altered shapes of OGTT curves, impaired insulin action and hyperinsulinemia due to increased secretion and attenuated hepatic extraction." (PMID 27505055, 2016). "This overproduction of insulin by the pancreatic β cells and a concomitant increase in serum insulin levels is a condition called hyperinsulinemia." (PMID 26720346, 2015). "Interference in glucose homeostasis interrupts extracellular and intracellular glucose concentrations, consequently amplifying insulin production by the pancreas, leading to hyperinsulinemia." (PMID 25821506, 2015). "Metformin is an insulin-sensitizing drug, usually prescribed in patients with PCOS, to induce ovulation, reduce the symptoms of hyperinsulinemia, and improve insulin sensitivity to decrease the serum levels of androgen." (PMID 26577050, 2015). "Before starting the treatments, all diabetic rats showed higher serum insulin levels (hyperinsulinemia) compared to the control rats." (PMID 25838947, 2015). "HFD progressively elevated blood insulin, giving rise to a significant level of hyperinsulinemia at the end of the experiment." (PMID 25768847, 2015). "In fact, after a singleexercise session, hyperinsulinemia promotes diminished sympathetic activity even thoughincreased vasodilatation in muscles is observed as a consequence of hemodynamic changesand insulin resistance is improved." (PMID 26421869, 2015). "In mice, a triple knockout of NPY1R, NPY2R and NPY4R prevents the hyperinsulinemia associated with NPY overexpression, indicating that NPY signalling through the NPY receptors modulates insulin secretion." (PMID 26138755, 2015). "High blood glucose levels, hyperinsulinemia (in the early stages), and low insulin sensitivity are the salient features of DM." (PMID 26347892, 2015). "Only fasting insulin was assessed in the current study; however, early onset of hyperinsulinemia with HF diet was only observed in the C57BL/6N mice with an intact, functional Nnt." (PMID 26146567, 2015). "As regards IR and hyperinsulinemia evaluation, although the glucose-insulin relationship is clinically relevant, it is also important to recognize that, theoretically, IR responds to influences other than glucose metabolism." (PMID 25977937, 2015). "In turn, the compensatory glucose metabolism associated with CypD deletion resulted in improved glucose tolerance, expansion of insulin-producing islet β cells, and sustained hyperinsulinemia, in vivo." (PMID 26515038, 2015).
Hyperinsulinemia (continued). "One consequence of IR and chronic peripheral hyperinsulinemia is down-regulation of insulin transport into the brain, eventually leading to a brain insulin deficient state." (PMID 26340637, 2015). "Insulin stimulates breast cancer cell growth and survival in vitro, and hyperinsulinemia is an adverse prognostic factor in breast cancer." (PMID 25849721, 2015). "The documented hyperinsulinemia in these patients, in the settings of diminished IS levels, suggests the existence of a significant residual insulin secretion capacity." (PMID 26089903, 2015). "We found hyperinsulinemia, impaired glucose and insulin tolerance in SKO mice, as reported in previous study." (PMID 26690553, 2015). "Impaired insulin action stimulates compensatory secretion of more insulin from pancreatic β cells when they are adequate to function, resulting in hyperinsulinemia." (PMID 27417763, 2015). "Previous studies have demonstrated that mixed isomer CLA supplementation in obese Zucker rats can improve insulin sensitivity and inflammation, and recently, that a CLAc9,t11 naturally enriched butter prevented high-fat diet induced hyperinsulinemia in rats." (PMID 26415741, 2015). "Diabetic patients are exposed to endogenous hyperinsulinemia both in the pre-diabetic state and at the early stages of the disease, but also when treated with insulin or insulin analogs at later stages of the disease." (PMID 25798130, 2015). "Patients with T1D were using subcutaneous insulin treatment, thus hyperinsulinemia pharmacologically induced by insulin must be taken into consideration." (PMID 26317989, 2015). "The mice gradually became resistant to the effects of insulin as the receptors that bind to the hormone become less sensitive to insulin concentrations resulting in hyperinsulinemia and disturbances in insulin release." (PMID 26599323, 2015). "Hepatic Timp1 expression is increased by euglycemic hyperinsulinemia in both insulin-sensitive and insulin resistant rats." (PMID 26168159, 2015). "Evidence for a role of PI3K-C2γ in the control of insulin metabolism emerged from the observation that Pik3c2g−/− mice develop age-dependent glucose intolerance and marked hyperinsulinemia." (PMID 26100075, 2015). "Overproduction of glucose during hyperinsulinemia in men with fatty liver results from inadequate suppression of all the supporting fluxes of glucose production in response to insulin." (PMID 25250633, 2015). "The liver is more exposed to hyperinsulinemia than any other tissue because insulin is transported via the portal vein." (PMID 26694382, 2015). "Hyperinsulinemia leads to increased lipolysis, ectopic deposition of fat in liver and skeletal muscles decreased glucose uptake into adipocytes by inhibition of the insulin-signaling pathway." (PMID 26061760, 2015). "Insulin treatment on a daily basis between 8 and 11 days after birth also increased body weight gain, impaired glucose tolerance, chronic hyperinsulinemia, and hypertension in later life." (PMID 26561832, 2015). "This insulin-desensitizing effect of prolonged hyperinsulinemia is likely at least partially mediated via ceramide accrual." (PMID 26682540, 2015). "Metformin and rosiglitazone are useful in AN characterized by IR; they reduce glucose production by increasing peripheral insulin responsiveness, reducing hyperinsulinemia, body weight, and fat mass and improving insulin sensitivity in peripheral muscles." (PMID 25977937, 2015). "drop in fasting insulin levels was observed; after the follow-up period of 6 months, fasting hyperinsulinemia was diagnosed only in 6 (15 %) patients." (PMID 25261984, 2015). "The fact that insulin resistant states lead to an increase in the expression of asthma related genes in spite of accompanying hyperinsulinemia and the fact that a low dose insulin infusion leads to the suppression of these genes need to be explained." (PMID 25642424, 2015).
Hyperinsulinemia (continued). "Milk and dairy products have been identified as potent insulin secretagogues, as their consumption stimulates acute hyperinsulinemia." (PMID 25710041, 2015). "First, during hyperinsulinemia, the glucose-infusion rate necessary to maintain euglycemia was higher in KO mice than in WT mice, indicating that insulin-stimulated glucose uptake and metabolism were active in KO mice." (PMID 26466345, 2015). "Persistently elevated insulin levels, immaterial of its origin, can result in insensitivity of its target cells over time, which further exacerbates hyperinsulinemia and increases the potential for beta cell dysfunction." (PMID 26225266, 2015). "The Lepr−/− rats showed significant hyperinsulinemia at baseline and presented a dramatic increase in serum insulin levels at 2, 4 and 8 months of age in both genders after the glucose loading." (PMID 26537785, 2015). "Accordingly, a state of hyperinsulinemia ensues due to the requirement of increased amounts of insulin to suppress hepatic glucose output from the liver and promote clearance of glucose into peripheral tissues." (PMID 25961014, 2015). "Numerous investigators have found that as much as 75% of the hyperinsulinemia in obese, insulin resistant patients, appeared to be the result of decreased hepatic insulin clearance, a phenomenon also noted in dysmetabolic monkeys." (PMID 25954816, 2015). "In 19 patients with morbid obesity (48,71 %) fasting insulin levels exceeding 15μIU/mL and suggesting hyperinsulinemia." (PMID 25261984, 2015). "We demonstrated that the combination therapy with canagliflozin and pioglitazone markedly improved hyperinsulinemia in established diabetic KK-Ay mice, implying improved insulin sensitivity." (PMID 25615826, 2015). "The detection of glucose isotopomers with 13C from [U-13C3]propionate is direct evidence for continuous gluconeogenesis from the citric acid cycle during hyperinsulinemia (plasma insulin > ∼100 μU/mL)." (PMID 25250633, 2015). "The biochemical markers of endogenous hyperinsulinism documented in this case suggest unique rates of disappearance of insulin and its precursors in patients with ESRD." (PMID 26664768, 2015). "Our work-up to differential diagnosis showed hyperinsulinism (high insulin plasma level, hypoketonaemia, hypofattyacidaemia at lower glucose level, high glucose requirement to maintain normoglycaemia, and positive glycaemic response to glucagon)." (PMID 26064751, 2015). "Studies showed a previous hyperinsulinism mechanism in diabetic subjects with acromegaly characterised by normal fasting glucose with rapid and persistent insulin response in OGTT, which became normal again later than seen in normal conditions or IGT/ IFG." (PMID 26361517, 2015). "Insulin was measured by radioimmunoassay; IAB and anti-IAB reagents competitively bound, which caused spurious hyperinsulinemia." (PMID 25289063, 2014). "Reduced insulin sensitivity and compensatory hyperinsulinemia play key etiologic roles in the development of NAFLD." (PMID 24397589, 2014). "Improved insulin sensitivity (reduced hyperinsulinemia) with CNX-012-570 was translated into reduced glucose intolerance and fed glucose levels in both DIO mice and db/db mice study respectively." (PMID 24460834, 2014). "In the last 40 min of the clamp the hyperinsulinemia suppressed the secretion of insulin by the pancreas, as well as lipolysis, and decreased hepatic glucose production to 10–15 %." (PMID 23934358, 2014). "Knockout of IDE gene leads to hyperinsulinemia in mice from impaired insulin clearance in multiple tissues." (PMID 24740421, 2014). "A gene trap insertion in Alms1 on the insulin sensitive C57BL6/Ei genetic background leads to early hyperinsulinemia and a progressive increase in body weight." (PMID 25299671, 2014).
Hyperinsulinemia (continued). "The question of how these affect glucocorticoid-induced insulin dependent processes, including hyperinsulinemia and lipid metabolism following an early-life stress exposure will be addressed in the following section." (PMID 24860550, 2014). "These values indicate a marked decrease in the liver insulin clearance, which mostly explains the hyperinsulinemia." (PMID 25101998, 2014). "The regulatory role of insulin and the effect of chronic hyperinsulinemia in increased leptin levels are another mechanism which remains to be clarified." (PMID 24563869, 2014). "It is generally believed that Pioglitazone reduces hyperinsulinemia through improvement of peripheral insulin sensitivity." (PMID 24740421, 2014). "Hyperinsulinemia initially presented in obese rats at 2 months (10.5 ± 0.7 μg/L plasma insulin vs. 0.2 ± 0.04 μg/L in lean) and decreased at 3 months (3.9 ± 0.6 vs. 0.5 ± 0.09 μg/ml in lean)." (PMID 24477469, 2014). "Insulin and IGF-1 are peptide hormones that stimulate proliferation of tissues and levels higher than normal (i.e. hyperinsulinemia) have been linked with carcinogenic properties in animal models." (PMID 24911052, 2014). "In an insulin resistant state, serum insulin levels are increased to a hyperinsulinemia state that activates the Akt/IKK signaling pathway, and thus activates NF-κB, a core transcription factor involved in the inflammatory response in non-metabolic organs." (PMID 25239110, 2014). "IGFBP-1 is regulated at transcriptional level by insulin and low fasting levels are a marker of hyperinsulinemia." (PMID 25461385, 2014). "In the high fat diet induced hyperlipidemic hamsters, 5-week treatment with ZBH significantly lowered serum triglyceride, total cholesterol, LDL-C, FFA, hyperinsulinemia, and improved insulin sensitivity more potently than bezafibrate." (PMID 24759758, 2014). "Postprandially, a rapid increase in blood glucose content stimulates insulin secretion, resulting in a temporary increase in blood insulin concentration known as hyperinsulinemia." (PMID 25019091, 2014). "In the face of peripheral hyperinsulinemia, insulin transport across the blood brain barrier is effectively reduced, resulting in a brain hypo-insulinemic state." (PMID 25071557, 2014). "The blood plasma analysis of the HFD animals showed hyperinsulinemia and hypertriglyceridemia confirming insulin-resistant conditions." (PMID 24638096, 2014). "If hyperinsulinemia is related to resistance of neuronal cells to insulin, impaired insulin signaling in neurons is thought to lead to neuronal disturbances." (PMID 25368578, 2014). "Yet, given that glucagon modulates insulin release, the potential contribution of altered glucagon levels to the β-cell hypersecretion and hyperinsulinemia of GC-treated subjects remains to be investigated." (PMID 24705399, 2014). "Although insulin in compensatory hyperinsulinemia has adverse mitogenic and proinflammmatory effects, at normal physiologic concentrations, preserved sensitivity to insulin signaling has a protective effect in the vasculature." (PMID 25352918, 2014). "Mice on HF displayed baseline hyperinsulinemia and a blunted in vivo glucose-stimulated insulin secretory response." (PMID 24505268, 2014). "In agreement, maternal deprivation induced early adulthood hyperinsulinemia and impairments in insulin sensitivity, measured through HOMA-IR, in male offspring fed with an HFD relative to HFD controls." (PMID 24860550, 2014). "Hyperinsulinemia, a condition in which there is an excess level of insulin circulating in the blood, in women with PCOS leads to anovulation, impairs folliculogenesis, and affects follicular development." (PMID 24520334, 2014). "Hyperinsulinemia initially present in obese rats at 2 months (10.5 ± 0.7 μg/L plasma insulin vs 0.2 ± 0.04 μg/L in lean) decreased due to ß-cell insufficiency at 3 months (3.9 ± 0.6 vs. 0.5 ± 0.09 μg/ml in lean)." (PMID 24477469, 2014).